DCP1A (decapping mRNA 1A)
Diseases named in the same sentence as DCP1A in open-access papers:
DCP1A is named in the same sentence as 48 diseases in open-access papers, as found by Europe PMC text mining. Sharing a sentence is not in itself a finding about the gene and the disease. The quoted sentences say what the papers report.
colorectal cancer (4 papers, 2021 to 2023). A primary or metastatic malignant neoplasm that affects the colon or rectum. "For instance, MALAT-1 expression was distinctly upregulated in colorectal carcinoma, and its knockdown suppressed colorectal carcinoma cells' metastasis and proliferation via sponging miR-203/DCP1A axis." (PMID 34858541, 2021).
viral infection (3 papers, 2015 to 2025). "Western blotting revealed that only cells coexpressing 3Cpro and DCP1A exhibited a cleavage band identical to that observed during viral infection." (PMID 40022242, 2025). "The replication of VSV-GFP was significantly inhibited in DCP1A-expressing cells, suggesting that overexpression of DCP1A inhibited viral infection." (PMID 37283741, 2023). "The decapping complex protein Dcp1a is a PB component targeted by virus infection." (PMID 26610553, 2015).
adenoma (2 papers, 2015 to 2020). A neoplasm arising from the epithelium. "In order to determine whether TTP loss in CRC is associated with P-bodies alteration, we analyzed the expression of TTP and the P-body marker Dcp1a in normal human colon, adenoma, and adenocarcinoma FFPE tissue arrays." (PMID 26343742, 2015).
cervical carcinoma (2 papers, 2020 to 2025). A carcinoma arising from either the exocervical squamous epithelium or the endocervical glandular epithelium. "A pioneering study demonstrated that AS-IV could suppress the progression of cervical cancer by activating the Atg7/Atg12/LC3 autophagy axis through targeting DCP1A and TMSB4X." (PMID 41155562, 2025). "The results suggested that the progression of AS-IV in the suppression of cervical cancer invasion is related to cell signaling transduction, secondary metabolite biosynthesis, and transmembrane transport, and especially might target DCP1A and TMSB4X." (PMID 32265995, 2020). "DCP1A and TMSB4X, the two proteins regulating autophagy, increased in cervical cancer cells when treated with AS-IV." (PMID 32265995, 2020). "Our results showed that the protein expression of DCP1A and TMSB4X increased in cervical cancer cells in the presence of AS-IV." (PMID 32265995, 2020). "We also found that AS-IV could target the proteins DCP1A and TMSB4X and induce autophagy in suppressing cervical cancer invasion." (PMID 32265995, 2020). "While DCP1A and TMSB4X may be regarded as targets of AS-IV in the process of autophagy, they also may be regarded as targets in the screening of anticancer compounds used in the treatment of cervical cancer." (PMID 32265995, 2020). "Thus, DCP1A and TMSB4X may be regarded as the targets of cervical cancer treatment." (PMID 32265995, 2020).
gastric cancer (2 papers, 2020 to 2021). A primary or metastatic malignant neoplasm involving the stomach. "Resistance of gastric cancer cells to chemotherapy can be abrogated by downregulation of DCP1A expression." (PMID 34609335, 2021). "LINC00339 could promote gastric cancer progression by increasing DCP1A expression level via inhibiting miR-377-3p." (PMID 32793467, 2020).
hepatocellular carcinoma (2 papers, 2021 to 2022). A malignant tumor that arises from hepatocytes. "We found two intronic variants with allele frequency <0.45 and 2 upstream variants within the TFBS of DCP1A, which is a biomarker used for gastric, colorectal, and hepatocellular cancer progression." (PMID 36011407, 2022).
malignant melanoma (2 papers, 2015 to 2021). "Further, DCP1A is highly expressed in malignant melanoma and its high expression in malignant melanoma is correlated with poor prognosis." (PMID 34609335, 2021).
thymoma (2 papers, 2021 to 2024). A neoplasm arising from the epithelial cells of the thymus. "The DCP1A has prognostic significance in kidney renal clear cell carcinoma (KIRC), rectum adenocarcinoma (READ) and thymoma (THYM), the high expression of DCP1A were associated with the observed favorable prognosis." (PMID 34609335, 2021).
adenovirus infection (1 paper, 2023). "Dcp1a is a target for other viruses that mediate PB disassembly; for example, infection with poliovirus caused PB disassembly and the loss of Dcp1a over a time course of infection and adenovirus infection has been shown to re-localize Pat1b from PBs to cytoplasmic aggresomes during infection." (PMID 36634147, 2023).
adrenocortical carcinoma (1 paper, 2021). "It was evidently noted that there was a positive correlation between DCP1A and PRKCD in all cancers, except adrenocortical carcinoma (ACC), uterine carcinosarcoma (UCS) and brain lower grade glioma (LGG)." (PMID 34609335, 2021).
cholangiocarcinoma (1 paper, 2021). A carcinoma that arises from the intrahepatic biliary tree (intrahepatic cholangiocarcinoma) or from the junction, or adjacent to the junction, of the right and left hepatic ducts (hilar cholangiocarcinoma). "Four of the other cancers (cholangiocarcinoma CHOL), colon adenocarcinoma (COAD), esophageal carcinoma (ESCA) and stomach adenocarcinoma (STAD) showed a high expression of DCP1A as compared with normal tissues." (PMID 34609335, 2021).
leukemia (1 paper, 2015). A malignant (clonal) hematologic disorder, involving hematopoietic stem cells and characterized by the presence of primitive or atypical myeloid or lymphoid cells in the bone marrow and the blood. "Similar results were obtained in U937 leukemia cells under M1-skewing conditions, in which a decrease in EDC4 or Dcp1a expression suppressed the IL-6 production without severely altering the mRNA level." (PMID 25970328, 2015).
liver cancer (1 paper, 2021). An epithelial or non-epithelial malignant neoplasm that arises from the liver. "Analysis showed that DCP1A was highly expressed in liver cancer tissues and its expression level was positively correlated with expression of PRKCD (P<0.05) in which was consistent with the findings using TCGA dataset." (PMID 34609335, 2021). "Therefore, as the target gene of eRNA DCP1A, they could play a synergistic role in promoting the progression of liver cancer." (PMID 34609335, 2021).
metastasis (1 paper, 2024). The spread or migration of cancer cells from one part of the body (where they first appeared) to another. "In CRC, DCP1A expression is elevated, which is associated with advanced TNM stages, lymph node metastasis and poor prognosis, and overexpression of DCP1A enhances P-body formation." (PMID 39046443, 2024).
non-small cell lung carcinoma (1 paper, 2024). A group of at least three distinct histological types of lung cancer, including non-small cell squamous cell carcinoma, adenocarcinoma, and large cell carcinoma. "The leading genes contributing towards a higher targeting of RNA degradation among males include CNOT1, CNOT2, CNOT3 and DCP1A, all of which have previously been found to have prognostic significance in various cancers, including non-small cell lung cancer." (PMID 39107837, 2024).
osteosarcoma (1 paper, 2025). A usually aggressive malignant bone-forming mesenchymal neoplasm, predominantly affecting adolescents and young adults. "In that experiment, we used DCP1A as a PB marker and treated U2OS cells (a human osteosarcoma epithelial cell line) with 2 mM Leu-Leu-O-Me (LLOMe), a well-characterized lysosome-damaging agent, for 30 min." (PMID 40964023, 2025).
spinocerebellar ataxia (1 paper, 2016). "Mutations in this gene have been associated with spinocerebellar ataxia and platelet signaling pathways, and DCP1A is known to play a role in mRNA decay and also in prematurely terminating protein synthesis." (PMID 27039371, 2016).
cancer (10 papers, 2015 to 2025). A tumor composed of atypical neoplastic, often pleomorphic cells that invade other tissues. "The results of pan-cancer survival analysis showed that the expression level of DCP1A was associated with the OS of patients with KIRC, READ, and THYM." (PMID 34609335, 2021). "Furthermore, the downregulation of DCP1a in multiple cancer types further supports the concept that DCP1a is a cancer-associated gene and suggests that its dysregulation may play a contributory role in the onset and progression of diverse cancers." (PMID 39485278, 2024). "They reported that the expression levels of DCP1A were reduced in various cancers including LUAD and LUSC, and the higher expression level of DCP1A was associated with a longer progression-free interval." (PMID 40200093, 2025). "This panel provides insights into the potential roles of DCP1a and DCP1b in different cancers, highlighting their differential expression patterns." (PMID 39485278, 2024). "Results for the GO, KEGG, and REACTOM pathways likewise showed that DCP1a is involved in other cancer-related pathways, such as the Notch signaling pathway, embryonic skeletal system development, vasculature development, and the mitotic cell cycle pathway." (PMID 39485278, 2024). "The prognostic significance of DCP1A in pan-cancer data was explored using Kaplan-Meier and log-rank tests." (PMID 34609335, 2021). "A pan-cancer analysis was carried out using the 32 other types cancers data from TCGA as the internal verification to further investigate the expression of DCP1A in a variety of cancers and its correlation with the target gene PRKCD." (PMID 34609335, 2021). "The results of pan-cancer analysis showed that the expression of DCP1A was differentially expressed in 13 other types of tumor tissues and their corresponding normal tissues." (PMID 34609335, 2021). "The findings showed increased expression of DCP1A was significantly correlated with the cancer status (P=0.0087), histological grade (G3/G4 vs G1/G2, P<0.001), AJCC stage (stage III/IV vs stage I/II, P=0.0067) and T stage (T3/T4 vs T1/T2, P=0.017)." (PMID 34609335, 2021). "The findings showed differential expression of DCP1A between 13 different types of cancer and the corresponding normal tissues." (PMID 34609335, 2021). "The levels of eIF4E (a c-Myc target gene) which is involved in cytoplasmic mRNP processing, were significantly reduced in carcinoma cells, as were the levels of Dcp1a, another constituent of P-bodies." (PMID 25669982, 2015). "In addition, several studies revealed the role of RNA decapping enzymes DCP1A and DCP2 in tumors and their association with the prognosis of cancer patients." (PMID 40200093, 2025). "Together with the observation of dysregulation of DCP1b in numerous cancers, we speculate that DCP1b is also implicated in cancer pathogenesis, and further studies are required to fully understand the roles of DCP1a and DCP1b in cancer pathogenesis." (PMID 39485278, 2024). "While DCP1a and DCP1b have both been implicated in cancer, our observation of significant alterations in multiple cancer-related pathways in DCP1a-knockout cells suggests that DCP1a might be more prominently associated with cancer development." (PMID 39485278, 2024). "A pan-cancer analysis was performed to explore the possible role of DCP1A in other cancer types." (PMID 34609335, 2021). "In addition, DCP1A was positively correlated with expression of PRKCD in all cancers except ACC, USC, and UGG." (PMID 34609335, 2021). "We found that AS-IV upregulated Atg12 and induced cancer cell autophagy through DCP1A and TMSB4X." (PMID 32265995, 2020). "The results showed that the expression of DCP1A and PUF60 were both higher in cancer tissue than that in adjacent tissue." (PMID 37632669, 2024). "The correlation between eRNA DCP1A and its predicted target gene PRKCD in different types of cancer was also verified." (PMID 34609335, 2021).
cancer (continued). "Interestingly, DCP1A also know as TF SMIF is the most enriched TF in this group, its protein is expressed the most in colon RKO cancer cells according to the MaxQuant database." (PMID 25477382, 2015). "Based on these findings, the ceRNA axes involving OIP5-AS1/hsa-miR-204-5p/BIRC5, DCP1A/hsa-miR-204-5p/BIRC5, and PPP1R9B/hsa-miR-204-5p/BIRC5 appear to play a crucial role in the progression of HCC, suggesting potential avenues for targeted therapeutic interventions in this type of cancer." (PMID 38283837, 2023).
infection (10 papers, 2015 to 2025). The state of being infected such as from the introduction of a foreign agent such as serum, vaccine, antigenic substance or organism. "In this study, we identified porcine DCP1A as an anti-SVV infection factor that targets 3D viral RNA-dependent RNA polymerase for autophagic degradation." (PMID 40022242, 2025). "Confocal microscopy revealed that SVV infection disrupts the subcellular localization of DCP1A." (PMID 40022242, 2025). "In addition, we examined the cleavage effect of SADS-CoV on DCP1A at different time points of infection in ST cells." (PMID 37283741, 2023). "Additionally, a form of DCP1A with a mutation in the glutamine 343 residue is resistant to nsp5-mediated cleavage and has a stronger ability to inhibit SADS-CoV infection than wild-type DCP1A." (PMID 37283741, 2023). "Here, we found that DCP1A is a possible target of SADS-CoV during infection." (PMID 37283741, 2023). "However, 2Apro-mediated disruption of PB was surprising, as we have previously determined it does not cleave the three PB constituents we found that undergo degradation during infection (Xrn1, Dcp1a, or Pan3)." (PMID 26610553, 2015). "DCP1A knockdown increased viral titers and viral VP1 protein production at 6, 9, 12, and 24 h post-infection (hpi)." (PMID 40022242, 2025). "We show that following host infection, SADS-CoV nsp5 uses its protease activity to cleave DCP1A at residue Q343, and nsp5 from many different coronavirus species can also cleave DCP1A." (PMID 37283741, 2023). "The localization of NS1 and XRN1 in A549 cells during a time course of WSN infection was studied using anti-XRN1 (green color), anti-NS1 (red color), and anti-DCP1A (purple color) antibodies in an immunofluorescence assay (IFA) by confocal microscopy." (PMID 34311580, 2021). "As for positive strand viruses, infection with EMCV and poliovirus (PolioV) at early time points, similarly stimulated the aggregation of XRN1 and DCP1a." (PMID 32034313, 2020). "To evaluate whether EBOV replication depends on decapping components other than EDC4, we tested the impact of knockdowns of DCP1A, B and DCP2 and accessory decapping protein EDC3 on infection efficiency." (PMID 41006235, 2025). "Since steady-state levels of the decapping cofactor, Dcp1a, decreased in response to KapB infection and Torin treatment, we examined the steady-state level of Dcp1a after Torin with and without NDP52 silencing." (PMID 36634147, 2023). "Imaging of Dcp1a foci showed that lytic reactivation of WT EBV resulted in a large (6-fold) decrease in the number of p-bodies, and that, relative to WT infection, the p-body numbers increased 2-fold in lytic infection with the BGLF2 KO." (PMID 35007297, 2022). "Except for DCP1A and ZAP (ZC3HAV1), most ISGs in the YC-2020 group showed a significantly lower expression than the JXA1 group, and gaps widened with the continuance of infection, which imply that YC-2020 may possess a more powerful capacity to weaken the host’s antiviral responses." (PMID 36338035, 2022). "Further analysis revealed that infection with Adeno-5 or HSV-1 failed to stimulate cytoplasmic aggregation of XRN1 and DCP1a." (PMID 32034313, 2020).
tumor (3 papers, 2021 to 2024). "The up-regulation of DCP1A was associated with advanced tumor stage, larger tumor size and higher histological grade." (PMID 34609335, 2021). "Functional analysis showed that high expression level of DCP1A was implicated in multiple tumor-related signaling pathways." (PMID 34609335, 2021). "The expression of DCP1A was differentially expressed in 13 other types of tumor tissues and its corresponding normal tissues (P<0.05)." (PMID 34609335, 2021). "Findings from univariate analysis showed that tumor stage, T stage, M stage, and DCP1A expression were predictors of OS in HCC patients (P<0.05)." (PMID 34609335, 2021). "The expression of DCP1A was also positively correlated with various tumor infiltrating immune cells." (PMID 34609335, 2021). "The findings showed that DCP1A was significantly highly expressed in tumor tissues compared with the expression level in normal tissues (P<0.001)." (PMID 34609335, 2021). "Expression of DCP1A was up-regulated in four tumor types (CHOL, COAD, ESCA, and STAD) whereas DCPIA expression was significantly down-regulated in 9 of tumor types." (PMID 34609335, 2021). "GSEA analysis showed that high expression level of DCP1A was correlated with significant enrichment of different of tumor-related signal pathways." (PMID 34609335, 2021). "Furthermore, high DCP1A expression was correlated with unfavorable clinical features, such as advanced tumor stage, tumor size (T stage), and higher histological grade." (PMID 34609335, 2021). "Further, results of this study also indicate that DCP1A have a significant correlation with tumor." (PMID 34609335, 2021). "By reexpression of PNRC1 or knockdown of P-body core genes (DDX6, DCP1A, and LSM14A), we determined that disruption of P-bodies attenuates cell proliferation, cell migration, and tumor growth induced by overexpression of YAP5SA in CRC." (PMID 39046443, 2024). "This translocation of DCP1A/DCP2 also leads to disassembly of P-bodies; thus, PNRC1 could also inhibit tumor cell proliferation by disrupting P-body formation." (PMID 39046443, 2024). "Moreover, analysis showed that all the four tumor tissues (CHOL, COAD, ESCA, and STAD) with high expression level of DCP1A were digestive system tumors." (PMID 34609335, 2021).
digestive system tumors (1 paper, 2021). "DCP1A plays a role as an oncogene in digestive system tumors with high expression level indicating poor prognosis thus it is a potential therapeutic target." (PMID 34609335, 2021).
DCP1A also shares sentences with these, for which no sentence is quoted: bladder urothelial carcinoma (2 papers); breast invasive carcinoma (2); lung adenocarcinoma (2); lung squamous cell carcinoma (2); pancreatic cancer (2); prostate adenocarcinoma (2); thyroid cancer (2); uterine corpus endometrial carcinoma (2); adenocarcinoma (1); bladder cancer (1); bone osteosarcoma (1); cervical squamous cell carcinoma (1); colon adenocarcinoma (1); colorectal neoplasm (1); endocervical adenocarcinoma (1); esophageal carcinoma (1); glioblastoma (1); glioma (1); gynecological tumor (1); head and neck squamous cell carcinoma (1); lung carcinoma (1); paraganglioma (1); pheochromocytoma (1); rectum adenocarcinoma (1); renal cell carcinoma (1); small cell lung carcinoma (1); uterine carcinosarcoma (1).